PIK3CA (phosphatidylinositol-4,5-bisphosphate 3-kinase catalytic subunit alpha)
Diseases named in the same sentence as PIK3CA in open-access papers (continued):
Sharing a sentence is not in itself a finding about the gene and the disease.
cancer (continued). "Compared to normal esophageal tissue, PIK3CA was significantly overexpressed in cancer tissue (P<0.001)." (PMID 25054828, 2014). "It has been reported that BT474 and MDA-MB-361 are Her2 high-expressing, and BT20 and MDA-MB-231 are Her2 low-expressing cancer cells, and that BT20, MDA-MB-361, and BT474 have mutations in PIK3CA, and only MDA-MB-231 has KRAS mutation among these cell lines." (PMID 25159299, 2014). "Furthermore, we found that for one individual patient, both PIK3CA hot spot mutations may co-exist in different cells, providing further compelling evidence for independent and parallel acquisition of driver mutations by individual cancer cells." (PMID 25358515, 2014). "The concomitant occurrence of PIK3CA and KRAS mutations was reported previously in CRC and other human cancer types." (PMID 25367198, 2014). "Expression of a single additional oncogene, PIK3CA-H1047R, converted thecells into invasive cancer cells." (PMID 25527189, 2014). "These outcomes were significantly lower than those reported in the current study of patients with PIK3CA-mutation and/or PTEN-loss/mutation metastatic or recurrent carcinoma receiving matched therapy." (PMID 25426553, 2014). "The Phosphoinositide-3-kinase catalytic alpha (PIK3CA) incearsed activity has been observed in a number of human cancer types such as breast, colon, liver, brain, stomach and lung." (PMID 23874428, 2013). "Since cancer-specific gain-of-function mutations were reported in PIK3CA gene, which encodes the p110α PI3K, this isoform has been placed in the center of cancer research." (PMID 23459844, 2013). "The pathway, with oncogene PIK3CA and tumor suppressor PTEN (gene), is implicated in insensitivity of cancer tumors to insulin and IGF1, in calorie restriction." (PMID 23768168, 2013). "NVP-BEZ235 has entered phase I/II clinical trials in patients with advanced solid tumors and showed higher efficacy in cancers with PIK3CA mutant." (PMID 23533654, 2013). "On the other hand, recent studies uncovered an AKT-independent signalling pathway in PIK3CA mutant cancer cell with low AKT activation that involved PDK1-dependent activation of SGK3." (PMID 23408974, 2013). "The phosphatidylinositol-3-kinase α catalytic subunit (PIK3CA) gene is known to be involved in the pathogenesis of several types of human cancers through gene amplification, deletions or somatic missense mutations within the helical and catalytic domains." (PMID 22949056, 2012). "EGFR, FGFRs, PIK3CA, PIK3R1 and AKT1 are proto-oncogenes, frequently activated in cancer through gain-of-function mutations and/or overexpression." (PMID 24213504, 2012). "Genes such as MYC and PIK3CA, known to be activated in many cancers tend to show more micro-amplifications; others known to be inactivated in cancer such as RB1 and PTEN display comparatively more micro-deletions." (PMID 23284754, 2012). "It is important to note, however, that not all patients with tumors harboring PIK3CA mutations are sensitive to PI3K pathway inhibitor treatment, and, on the other hand, that also subsets of patients with wild-type PIK3CA/PTEN cancers are responsive." (PMID 22970424, 2012).
cancer (continued). "Since the EGFR and PIK3CA are among the most frequently activated oncogenes in cancer, we suggest that the specific anti-oxidant transcriptional program driven by these oncogenes protects and favours the selection of the cells carrying the mutated proteins." (PMID 22662165, 2012). "As cancer relapse occurs in the lymph nodes in most cases, the amplification of the PIK3CA copy number is likely to promote the process of lymph node metastasis in early-stage patients." (PMID 22994622, 2012). "More PIK3CA/AKT1 mutations and PIK3CA copy gain are identified in ATC as compared to well differentiated cancer, suggesting that PI3K/mTOR pathway activity is involved in the process of cancer de-differentiation." (PMID 23077520, 2012). "To date, we have limited information about the interference of the specific cancer mutations of EGFR and PIK3CA with metabolic responses of cells exposed to glucose deprivation." (PMID 22662165, 2012). "Mutation of either RAS or BRAF, or PIK3CA and PTEN, which are considered as initial mutations of the differentiated carcinomas are found in the majority of ATC." (PMID 23115614, 2012). "Alteration of PI3K family members, such as amplification of the phosphoinositide-3-kinase catalytic subunit alpha (PIK3CA) oncogene on chromosome 3q26 that encodes the p110α catalytic subunit of PI3K, are commonly observed in human cancers." (PMID 22033276, 2011). "The RAS, RAF, PIK3CA, AKT,ERBB1, KIT, FMS and ETS oncogenes are also contained as viral oncogenes in the genomes of certain retroviruses that cause cancer in animals." (PMID 21422497, 2011). "Some studies have suggested that PIK3CA mutant cancers are “oncogenically addicted” to PI3K signaling, leading to increased sensitivity to PI3K inhibitor therapy." (PMID 21966435, 2011). "The PIK3CA gene, which encodes the class IA PI3K catalytic subunit p110α, has been found to harbor mutations in several cancers." (PMID 22064833, 2011). "These genetic changes include CDKN2A deletion and MYC amplification in immortalization, HRAS activation in transformation, PIK3CA activation in the formation of malignant tumors, and RUNX1 deletion associated with poorly-differentiated malignant tumors." (PMID 20169162, 2010). "As well as identifying high frequency, differentially expressed genes, including known cancer genes such as PIK3CA and AURKA, we also used high amplitude regions to locate additional known (e.g. ERBB2 and CCNE1) and potential oncogenes." (PMID 20386695, 2010). "Moreover, the meta-analysis has the further advantage of providing an outlook and an estimate of PIK3CA exon-selectivity and standardized rate of mutation in different cancer types, although this might be affected by the limitations derived from retrospective studies." (PMID 20398348, 2010). "Pre-clinical studies have shown that PI3K pathway activation, through PIK3CA activating mutations or PTEN loss of function, significantly decreases the response of KRAS mutant cancer cells to MEK1/2 inhibitors." (PMID 20149254, 2010). "Several putative cancer-related genes at the 3q26.2–q29 regions were previously linked to specific histologic subtypes; specifically, gains at EVI1 and MDS1 (3q26.2),PIK3CA (3q26.32), and TP73L (3q28) were significantly observed in SCCs (P < 0.05)." (PMID 19607727, 2009). "The present data offers the evidence that NF-κB directly upregulates PIK3CA and provides a novel pathway through which NF-κB activation can promote cancer cell survival during stress." (PMID 18335034, 2008). "Previous studies on the function of PIK3CA have predominantly focused on regulatory circuitries within the cancer cell." (PMID 18335034, 2008).
cancer (continued). "Based on in silico prediction and in situ scanning, at least two stress signaling pathways appeared to play important roles in PIK3CA regulation in cancer, namely HIF and NF-κB." (PMID 18335034, 2008). "Expression of mutant p110αconferred more lipid kinase activity than expression of wild-typeprotein.These data suggested that mutant PIK3CA was likely to function asan oncogene in human cancers." (PMID 19384426, 2007). "The PIK3CA p110α catalytic subunit of PI3K will be highlighted in this review due to the recent alterations of this protein found in primary human cancers." (PMID 16449998, 2006). "Somatic activating mutations have been identified in multiple human cancers within these pathways, particularly in the BRAF and PIK3CA genes, respectively." (PMID 16822308, 2006). "The phosphatidylinositol 3-kinase signalling pathway has previously been implicated in tumorigenesis, and evidence over the past year suggests a pivotal role for the phosphatidylinositol 3-kinase catalytic subunit, PIK3CA, in human cancers." (PMID 16449998, 2006). "Recently, mutations in PIK3CA, which encodes the p110α catalytic subunit of PI3K, have been identified in various human cancers, including 3 of 12 gastric cancers." (PMID 15784156, 2005). "This hypothesis is supported by the fact that somatic cancers with PTEN-R173 variants, along with mutation of the WT allele of PTEN, also contain mutations in other cancer drivers such as PIK3CA." (PMID 41215730, 2026). "PIK3CA variations, along with other gene alterations, may influence cancer progression and could therefore play a crucial role in determining targeted treatment strategies." (PMID 41594221, 2026). "Activation of bypass signaling (via amplification or mutations of HER2, FGFR1, MET, and PDGFR) or downstream signaling (via mutations of NRAS, BRAF, PIK3CA, or deletion of PTEN) in cancer cells has been shown to contribute to resistance to anti-EGFR antibodies." (PMID 40362183, 2025). "This either suggests that PIK3CA mutations are not bona fide drivers or adds to evidence supporting its activity acting in a dose-dependent manner, with cancers only being able to tolerate a certain level of mutated PIK3CA activity." (PMID 40514689, 2025). "Therefore, developing p110α mutant-specific inhibitors to circumvent on-target side effects becomes a new direction for targeting PIK3CA mutant cancers." (PMID 39717717, 2025). "Although PIK3CA alterations contribute to the pathogenesis of HR+/HER2− BC and represent a target for several novel drugs, they are not intrinsically associated with unfavorable clinical characteristics of this subtype of cancer disease." (PMID 40507317, 2025). "Similarly, taselisib, assessed as monotherapy in the phase I clinical trial NCT01296555 in patients with PIK3CA-mutant cancers, showed a limited benefit in TNBC cohort (n = 17; 10.2%), with a median PFS of 3.0 months (95% CI: 1.6–4.2)." (PMID 40647529, 2025). "However, pan-AKT inhibitors have been applied against cancers with PIK3CA/AKT/PTEN alterations in clinical trials." (PMID 40008088, 2025). "Similarly, oncogenic mutations activating the PI3K–AKT–mTORC1 pathway (e.g., PIK3CA mutations, PTEN deletions) confer ferroptosis resistance in cancer cells by upregulating SREBP1 and its downstream effector, SCD1." (PMID 40427160, 2025). "Of note, all three PIK3CA mutations detected by WES, for which we could experimentally determine the cancer cell fraction (CCF), were clonal (CCF = 1)." (PMID 40846762, 2025). "Mutations in pTERT, GPR126, FGFR3, and PIK3CA are cancer-specific and are unlikely to occur in normal cells." (PMID 41515564, 2025).
cancer (continued). "CC cell lines harboring PIK3CA mutations exhibit greater sensitivity to alpelisib than non-mutated cancer cells or normal cells." (PMID 41256331, 2025). "PIK3CA is one of the most common mutated genes in patients with cancer and its association with cancer survival was investigated before with results showing no impact on survival." (PMID 40353995, 2025). "Pan-cancer studies have revealed a higher frequency of recurrent alterations in cancer driver genes, including PIK3CA, APC, PTEN, and MYC, and higher overall burden of copy number alterations, including whole genome duplication in metastases compared with primary tumors." (PMID 39416100, 2025). "The presence of PIK3CA mutations highlights a potential role for targeted therapy, with agents such as the PI3Kα inhibitor alpelisib and the pan-PI3K inhibitor copanlisib already being used for other cancers." (PMID 41301029, 2025). "The discovery that PIK3CA mutations activate the PI3K/AKT/mTOR pathway, which also plays a pivotal role in oncogenesis, has opened the door to repurposing targeted therapies initially developed for cancer." (PMID 40861611, 2025). "Patients with PIK3CA-mutant tumors may demonstrate improved responses to PI3Kα-specific inhibitors, such as alpelisib, when used in combination with cancer vaccines." (PMID 40266213, 2025). "Although PIK3CA alterations contribute to the pathogenesis of HR+/HER2− BC and represent a target for several novel drugs, they are not intrinsically associated with unfavorable features of this subtype of cancer disease." (PMID 40507317, 2025). "Nevertheless, PI3K/AKT pathway activation in cancer can also be enhanced by mechanisms other than alterations in PIK3CA/AKT1/PTEN14,25,26, supported by preclinical data showing that capivasertib inhibited growth in some cell lines without PIK3CA/AKT1/PTEN alterations." (PMID 40346047, 2025). "have demonstrated that PIK3CA amplification is a strong prognostic marker in several cancers." (PMID 41181577, 2025). "Using the TIMER 2.0 database, we conducted pan-cancer analysis of PIK3CA expression." (PMID 40723456, 2025). "Similarly, in our BCa study, mutual exclusivity between PIK3CA and MAP3K1 mutations and the loss of 13q14.2 raises intriguing questions about the functional redundancy or compensatory mechanisms within cancer cells." (PMID 39605038, 2024). "In this study, we analyzed multi‐PIK3CA mutant tumors across a diverse array of cancers." (PMID 39054873, 2024). "Interestingly, combined PIK3CA and SOX2 amplification allowed us to distinguish three cancer risk subgroups, and PIK3CA and SOX2 co-amplification was found the strongest predictor by ROC analysis." (PMID 38473941, 2024). "Mutations within the PIK3CA gene impact the p110ɑ catalytic subunit of the PI3K protein, disrupting the signaling pathway and leading to immune disorders, cardiovascular diseases, and cancer in various tissue types." (PMID 38671743, 2024). "Indeed, several studies have shown that mutations in key genes such as PIK3CA, FGFR, ERBB2, and PTEN are likely caused by A3 enzymes and are frequently observed in HPV-positive cancers." (PMID 39764440, 2024). "It was observed that PIK3CA was also associated with EGFR, this implies that E. acoroides Extract is also involved in pathways such as PI3K/AKT and HIF-1Alpha signaling which were recognized as cancer makers." (PMID 38474594, 2024). "Overall, our study suggests that the combination of alpelisib and capecitabine could be a promising treatment option for patients with PIK3CA mutant advanced cancers." (PMID 39070139, 2024).
cancer (continued). "Developing a comprehensive biomarker panel that includes PTGS2, PIK3CA, and HLA class I antigens could revolutionize the duration, dosing, and customization of aspirin therapy for cancer patients." (PMID 39445288, 2024). "Besides the secondary EGFR mutations, amplification, loss, and mutation of some other cancer-related genes also contribute to gefitinib resistance, such as MET, HER2, BRAF, and PIK3CA." (PMID 38472205, 2024). "Remarkably, PIK3CA amplification was found to be an independent cancer predictor." (PMID 38473941, 2024). "On this basis, the present study investigated the clinical significance of PIK3CA and SOX2 gene amplification in early stages of laryngeal tumorigenesis by evaluating their predictive value for cancer risk assessment in 62 patients with laryngeal precancerous lesions." (PMID 38473941, 2024). "Moreover, XPO1 and PIK3CA inhibitors, currently approved for the treatment of various cancer types, hold potential for repurposing as therapeutic agents for PD86,87." (PMID 39711693, 2024). "Moreover, several confirmed gender-related carcinogenic genes exhibit completely different distributions in male and female cancer samples, such as PIK3CA, NF1, EIF1AY, IGF1R, NRAS, KDM5D, UTY, and PPP6C." (PMID 39541191, 2024). "Furthermore, ASCC exhibited somatic missense mutations in cancer driver genes, with KMT2C, PIK3CA, and EP300 being the most mutated genes, in agreement with previous reports." (PMID 39024554, 2024). "ASP may therefore suppress CRC cancer cell growth and induce apoptosis by blocking the PI3K pathway through COX-2 inhibition, and this effect will differ according to PIK3CA mutational status." (PMID 38791419, 2024). "Furthermore, PIK3CA is a marker gene that is highly expressed in several cancer types, including breast, colon, ovarian, gastric, lung, brain, skin, and so on." (PMID 38666938, 2024). "We found that FOXO3, Nrf2, NQO1, Gpx4 and PIK3CA are not only related to regulating metabolic diseases, but also may have therapeutic effects on aging, cancer, or hyperuricemia." (PMID 38957396, 2024). "Therefore, further research with large cohorts is essential to robustly evaluate the association between the PIK3CA single/multiple mutation status and the prevalence of PTEN mutations across various cancer types." (PMID 39054873, 2024). "Furthermore, combined PIK3CA and SOX2 amplification is emerging as a valuable and easy-to-implement tool for cancer risk assessment in patients with laryngeal precancerous lesions beyond current WHO histological grading." (PMID 38473941, 2024). "Analysis of the Cancer Dependency Map (DepMap) classified PIK3CA to be a strongly selective dependency in other cancer types, however, MTOR was identified to be a common dependency in both healthy and cancerous cells, providing further justification for targeting PI3K in DIPG." (PMID 38319732, 2024).